RET (ret proto-oncogene)
Diseases named in the same sentence as RET in open-access papers (continued):
Sharing a sentence is not in itself a finding about the gene and the disease.
non-small cell lung carcinoma (continued). "Therefore, multiple kinase inhibitors targeting RET protein have been actively utilized to treat non-small cell lung cancer (NSCLC) and MTC." (PMID 34207842, 2021). "RET fusions occur in 1–2% of non-small cell lung cancer (NSCLC) cases." (PMID 31058838, 2019). "Moreover, the efficacy and safety of vandetanib in patients with advanced RET-rearranged non-small-cell lung cancer (NSCLC) was assessed in phase II trials." (PMID 30901976, 2019). "RET fusion genes were recently identified in a population of non-small cell lung cancers (NSCLCs)." (PMID 29088743, 2017). "For instance, RET fusions were recognized as oncogenic and drug-sensitive rearrangements in approximately 1-2% of lung adenocarcinoma and various multi-kinase inhibitors were actively investigated to treat non-small cell lung cancer." (PMID 26716414, 2016). "Non-small cell lung carcinoma (NSCLC) therapy has been transformed by the identification of actionable oncogenic driver mutations, of which ALK, ROS1, RET fusions and MET exon 14 skipping represent interesting drug targets." (PMID 38492039, 2024). "For example, the systemic treatment of advanced non-small cell lung cancer remained conventional chemotherapy for several decades until the emergence of TKI therapy following the discovery of several driver mutations including EGFR, ALK, ROS1, MET, RET, BRAF, and ERBB2/HER2." (PMID 39409947, 2024). "In addition to common EGFR activation mutations, targets such as ALK rearrangement, ROS1 rearrangement, RET rearrangement, BRAF V600E, MET exon 14 skip mutation, KRAS G12C, etc. have been gradually approved for targeted drug application in advanced non-small cell lung cancer." (PMID 38023198, 2023). "RET kinase domain fusion with kinesin family member 5B was identified in about 1–2% of patients with non-small-cell lung cancer (NSCLC), who were negative for mutations or rearrangements in other common oncogenic drivers such as EGFR, HER, ERBB2, BRAF, KRAS, ALK, etc.." (PMID 32993133, 2020). "RET fusions rather than mutations are typically present in non-small cell lung cancer (NSCLC)." (PMID 31058838, 2019). "Among current molecular targets for advanced non-small cell lung cancer (NSCLC) are c-Ros oncogene 1 (ROS1) and rearranged during transfection (RET), which code for tyrosine kinase receptors." (PMID 39907599, 2025). "For example, several fusion genes (ALK, ROS1, RET, and NTRK) are currently recommended actionable molecular biomarkers for non-small cell lung cancer (NSCLC) by the American Society of Clinical Oncology (ASCO) guidelines." (PMID 40938919, 2025). "In non-small cell lung cancer (NSCLC), identification of ALK, ROS1, or RET fusions provides access to tyrosine kinase inhibitors with substantial clinical benefit." (PMID 41228293, 2025). "Non-small cell lung cancer (NSCLC) is a significant global health challenge, with 2% of cases fuelled by RET rearrangements." (PMID 40405293, 2025). "A similar approach is taken toward MET, HER2, RET, ROS1, and FGFR alterations as emerging targets in non-small-cell lung cancer." (PMID 39941723, 2025). "For non-small cell lung cancer (NSCLC) the current clinical guidelines recommend testing for genomic alterations in EGFR, BRAF, ROS1, ALK, KRAS, NTRKs, MET, RET, and ERBB2 genes." (PMID 38398180, 2024). "Targeted therapy for non-small-cell lung cancer (NSCLC) involves drugs that inhibit angiogenesis, and inhibitors of kinases EGFR, ROS1, MET, and RET." (PMID 35740471, 2022). "Treatment planning for non-small cell lung cancer requires testing for EGFR, ALK, ROS1, BRAF, MET, RET and KRAS gene alterations." (PMID 34681592, 2021). "Gene mutations are often involved in tumorigenesis, the clustered deletions were found in ABL1, NOTCH1, RET, STK11, GNA11, and JAK3 genes in CRC, melanoma, and non-small cell lung cancers." (PMID 32850446, 2020).
non-small cell lung carcinoma (continued). "The National Comprehensive Cancer Network (NCCN) guidelines recommend “broad molecular profiling”, including BRAF, ERBB2 (HER2), MET, RET, NTRK, and ROS1, in addition to EGFR and ALK for metastatic non-small cell lung cancer (NSCLC)." (PMID 32375398, 2020). "Using a genomics guided outlier approach, we identified 4 RET fusion PDX models with 3 different fusion partners (KIF5B, CCDC6, and NCOA4) in both non-small cell lung cancer and colorectal cancer." (PMID 30038711, 2018). "Non-small cell Lung cancer is now a heterogenous disease with EGFR, BRAF, Her2/Neu aberrations or ALK, ROS1, RET or FGFR fusions." (PMID 26510912, 2015). "Somatic RET rearrangements (as fusion genes with CCDC6, NCOA4, KIF5B, PRKAR1A, TRIM33 and other rarer partners) have now been found in 1–2% of non-small-cell lung cancers (NSCLC) and at lower prevalence in many other cancers including pancreatic, colon, breast and salivary gland." (PMID 39655713, 2025). "Intrapleural injection of PD1 mAb has proven to be effective in managing MPE in mouse models and has also shown promising results in a small-scale human study, but no study was reported in non-small cell lung cancer patients with RET acquired resistance." (PMID 39372862, 2024). "Likewise, the evaluation of genes such as ALK, ROS1, RET, and HER2 is crucial in assessing non-small-cell lung cancer (NSCLC), as established in the National Comprehensive Cancer Network (NCCN) guidelines." (PMID 39338229, 2024). "For non-small cell lung cancer (NSCLC), this has led to the development of tyrosine kinase inhibitors (TKIs) specifically targeting the resulting fusion proteins, including ALK, ROS1, RET, and NTRK." (PMID 37016288, 2023). "In non-small cell lung carcinoma (NSCLC), Cabozantinib showed higher efficacy in RET-fusion patients, leaving open the hypothesis that an inhibitor may have different efficacy against RET mutation and/or rearrangement." (PMID 35631627, 2022). "Non-squamous NSCLC (Non-small-cell lung carcinoma) patients exhibit significant clinical benefits when treated with selpercatinib and pralsetinib, against RET gene fusions, demonstrated by LIBRETTO-001 and ARROW clinical trials." (PMID 35113898, 2022). "RET is a new driver gene discovered after EGFR and ALK in non-small cell lung cancer." (PMID 35211155, 2022). "Other sequence-based tests have been launched commercially that target common, potentially druggable oncogene fusions in ALK, RET, and ROS1 in non-small cell lung cancer (NSCLC), a test historically carried out by immunohistochemical assays such as fluorescence in situ hybridization." (PMID 27784341, 2016). "Clinical effectiveness of another mitotic-poisoning agent, docetaxel, was also improved in non-small-cell lung carcinoma (NSCLC) patients when used in combination with nintedanib, a non-selective inhibitor targeting all subtypes of VEGFRs, FGFRs, and PDGFRα and β, together with RET and FLT3." (PMID 41154409, 2025). "Mutations in SMARCA4 have been shown to co-exist with KRAS mutations but are mutually exclusive from common targetable non-small cell lung carcinoma (NSCLC) oncogenes, including EGFR, ALK, MET, ROS-1, and RET." (PMID 40406754, 2025). "In detail, proteasome for the regulation of protein expression, melanoma and non-small cell lung cancer for their neuroendocrine nature and phosphatidylinositol signalling system since phosphatidylinositol 3-kinase/protein kinase B (PI3K/AKT) activation triggered by RET has been observed in MTC." (PMID 37286863, 2023). "In non-small cell lung carcinoma (NSCLC), targeted therapies are mainly directed toward specific altered genes that have been thoroughly analyzed, including EGFR, ALK, ROS1, and RET." (PMID 37999148, 2023). "In non-small cell lung carcinoma (NSCLC), the gene fusions of ALK, NTRK, RET, and ROS1 are detected with the approximate frequencies of 4–6, 1, 1–2, and 1–2%, respectively." (PMID 32328458, 2020).
lung adenocarcinoma (137 papers, 2012 to 2026). A carcinoma that arises from the lung and is characterized by the presence of malignant glandular epithelial cells. "RET fusion-positive lung adenocarcinomas are associated with poor differentiation, solid sub-type, and smaller T stage (≤3 cm) with N2 disease." (PMID 36690680, 2023). "A KIF13A fusion with RET sequences encoding tyrosine kinase (KIF13-RET) has been reported in lung adenocarcinoma." (PMID 35547822, 2022). "RET is located in the long arm of human chromosome 10 and encodes a receptor tyrosine kinase protein, and RET fusion-positive lung adenocarcinoma occurs in 1%–2% of cases." (PMID 34497761, 2021). "To identify transcriptomic changes associated with RET expression, we analyzed RNA sequencing data obtained by The Cancer Genome Atlas (TCGA) for lung adenocarcinoma." (PMID 33318047, 2020). "We also investigate the anti-tumor activity of Apatinib, a potent inhibitor of VEGFR-2, PDGFR-β, c-Src and RET, in RET-rearranged lung adenocarcinoma, together with the mechanisms underlying." (PMID 27494860, 2016). "Moreover, clinical studies that combine RET inhibitors and EGFR TKIs with other targeted drugs are warranted for the lung adenocarcinoma patients harboring concurrent KIF5B-RET fusion gene and EGFR or KRAS mutations." (PMID 26268359, 2015). "Recently, transcription-dependent fusions of KIF5B-RET have been found to lead to aberrant activation of RET kinase in what could be considered to be a new driver mutation of lung adenocarcinoma." (PMID 23560038, 2013). "We herein report a case of a 71-year-old female with bilateral multiple primary lung adenocarcinomas, in which separate lesions harbored an EGFR 19del mutation and a RET fusion gene, demonstrating intratumoral genetic heterogeneity." (PMID 41821900, 2026). "The increasing use of targeted therapies for ALK, ROS1, and RET gene rearrangements has underscored the critical importance of routine genetic screening in patients with lung adenocarcinoma." (PMID 39810398, 2025). "We report the case of a 53-year-old man with recurrent RET-positive lung adenocarcinoma who developed CA 17 months after starting selpercatinib." (PMID 41346910, 2025). "We conducted a retrospective study of patients with advanced lung adenocarcinoma harboring ALK, ROS1, and RET fusions, comparing them with cohorts harboring EGFR mutations." (PMID 40751559, 2025). "We present a 59-year-old patient diagnosed with RET fusion-positive lung adenocarcinoma which had metastasized to the brain at the time of initial diagnosis, classified as stage IVB, cT3N3M1." (PMID 41018100, 2025). "In NSCLC, particularly lung adenocarcinoma, RET fusions are identified in approximately 1-2% of patients, most frequently among younger, non-smoking individuals." (PMID 41346910, 2025). "Targeted therapies directed at fusion proteins resulting from ALK, ROS1, RET, and other gene fusions underscore the importance of routinely identifying these alterations in patients with lung adenocarcinoma." (PMID 39810398, 2025). "This retrospective study aimed to investigate this association in advanced lung adenocarcinoma patients with ALK, ROS1, RET rearrangements, and EGFR mutations." (PMID 40751559, 2025). "Further studies across a much larger cohort of lung adenocarcinoma patient tissue samples add to our knowledge of RET fusions by investigating the prevalence of RET gene fusion partners." (PMID 41246330, 2025). "As KIF5B is considered a common fusion partner of RET in lung adenocarcinoma, the prediction of our XAI model is appropriate." (PMID 38791993, 2024). "Given that RET rearrangement is a driver alteration in lung adenocarcinoma, occurring in approximately 1–2% of NSCLC, they were included as an eligible molecular biomarker in our study." (PMID 39138436, 2024). "Herein, we present an interesting clinical case of a critical lung adenocarcinoma harboring RET fusions." (PMID 39372862, 2024).
lung adenocarcinoma (continued). "This case highlights the efficacy and tolerability of selpercatinib in treating advanced lung adenocarcinoma with a RET fusion." (PMID 39882443, 2024). "Here, we present a case highlighting the use and clinical outcomes of selpercatinib in a patient diagnosed with advanced lung adenocarcinoma harboring a RET fusion." (PMID 39882443, 2024). "Here, we report a patient with stage IIIA lung adenocarcinoma with a RET fusion gene and high expression of PD-L1 who underwent neoadjuvant chemoimmunotherapy and successfully attained a pathologic complete response." (PMID 38235141, 2024). "Using ponatinib as an MKI to counteract RET fusion-positive (CCDC6-RET) LC-2/ad lung adenocarcinoma cell growth, Nelson-Taylor and colleagues demonstrated that inhibition of RET phosphorylation is accompanied by ERK1/2 and AKT inactivation." (PMID 36768754, 2023). "Multiple genetic alterations have been identified as therapeutic targets in lung adenocarcinoma, including mutations in EGFR, ERBB2, BRAF, KRAS, and MET and rearrangements of ALK, RET, and ROS1." (PMID 37628603, 2023). "Recent studies have revealed the presence of RET rearrangements in 1–2% of cases of lung adenocarcinoma." (PMID 38132167, 2023). "We reported one case of transformation of a RET-rearranged lung adenocarcinoma to SCLC after selpercatinib treatment and explored its underlying mechanism using whole-exome sequencing (WES) technique." (PMID 38057798, 2023). "Herein, we report a novel progesterone immunomodulatory binding factor 1 (PIBF1)-RET gene fusion identified from a stage IA lung adenocarcinoma and was further validated by RNA sequencing analysis." (PMID 37478265, 2023). "REarranged during Transfection (RET) oncogenic rearrangements can occur in 1–2% of lung adenocarcinomas." (PMID 38132167, 2023). "Common driver mutations (EGFR, ALK, BRAF, ERBB2, KRAS, MET, RET, and ROS1) analysis were performed in lung adenocarcinoma tissue samples from two PEAC patients (P08 and P10) using next-generation sequencing." (PMID 35172862, 2022). "Of the two JCAD-RET cases, one had lung adenocarcinoma and the other were diagnosed with soft tissue sarcoma of the cervix, and both had the 5’ UTR of JCAD fused to the RET gene." (PMID 36369474, 2022). "RET fusion-positive lung adenocarcinoma occurs in 1%–2% of cases, and clinical trials of multikinase inhibitors that inhibit RET oncogene activity such as vandetanib and cabozantinib have indicated their antitumor efficacy." (PMID 34497761, 2021). "A study on the relationship between ionizing radiation with RET fusion in lung adenocarcinoma found that 201T human lung cells exposed to 1 Gy of gamma rays induced RET fusion, and RET rearrangement was also found in 2 of 37 cases of radiation exposure." (PMID 34381020, 2021). "The first report of response to cabozantinib in RET-fusion positive lung adenocarcinomas was described by Drilon and colleagues in three patients as preliminary data of a phase II trial." (PMID 33806299, 2021). "Certain clinical and imaging features derived from ALK/ROS1/RET fusion-positive lung adenocarcinoma patients were found to be good discriminators of fusion-positive and fusion- negative lung adenocarcinomas." (PMID 34164563, 2021). "Somatic mutations in EGFR and KRAS as well as chromosome rearrangements affecting ALK, ROS1, and RET have been identified in human lung adenocarcinoma (LUAD)." (PMID 33348616, 2020). "Other, less frequent mutations such as RET and ROS1, which comprise 1–2% of all lung adenocarcinomas, have also been assessed for associations with imaging features." (PMID 31901171, 2020). "Lung adenocarcinoma patients with WSE showed a distinctive mutated profile for the SMARCB1, ATM, EGFR exon 7, RET and KDR genes." (PMID 30093964, 2018). "The advent of therapies targeting the fusion proteins arising from ALK, ROS1, and RET gene fusions makes the routine detection of these events important in patients with lung adenocarcinoma." (PMID 30115026, 2018).
lung adenocarcinoma (continued). "Considering the roles of RET in thyroid and lung adenocarcinoma, as well as its potential contributions to regional spread and metastasis in other cancer types, our study raises perspectives for therapeutic intervention in multiple aggressive cancer diseases." (PMID 28122586, 2017). "NSCLC patients harboring rearrangements within the ALK, ROS1 and RET gene can be targeted in lung adenocarcinoma using specific therapies such as Crizotinib." (PMID 28404952, 2017). "The KIF5B-RET transgenic mice develop lung adenocarcinomas, indicating that RET fusion genes are oncogenic drivers of lung adenocarcinomas." (PMID 29088743, 2017). "Gain of function mutations in RET are implicated in several human cancers, e.g. medullary thyroid cancer (MTC) and lung adenocarcinoma (LAD)." (PMID 26874741, 2016). "Previously, we screened for ALK, ROS1, and RET fusion genes in 795 lung adenocarcinoma specimens and identified the novel KIAA1217-RET fusion gene containing KIAA1217 exon 11 and RET exon 11 from a patient with a 4-cm tumor mass (red arrow)." (PMID 27150058, 2016). "RET fusion genes in lung adenocarcinomas appear predominantly following intrachromosomal rearrangement." (PMID 27150058, 2016). "The overall prevalence of RET fusion in lung adenocarcinomas is 1−2% according to existing literatures, and it increases to 6−19% for tumors without other genetic variants." (PMID 27494860, 2016). "REarranged during Transfection (RET) fusion genes are detected in approximately 1% of lung adenocarcinomas and known primarily as oncogenic driver factors." (PMID 27150058, 2016). "In 2012, we first identified the existence of the Kinesin family member 5B (KIF5B)-RET fusion gene in a young male patient with lung adenocarcinoma using whole-genome and transcriptome sequencing analysis." (PMID 26268359, 2015). "Recent genomic studies in lung adenocarcinoma have identified other potential therapeutic targets, such as mutations in KRAS, HER2 and BRAF, ROS1 rearrangements, RET fusions and MET amplification." (PMID 25789627, 2015). "Cabozantinib, also a multi-kinase inhibitor and potent inhibitor of RET, demonstrated impressive activity in patients with RET fusion-positive lung adenocarcinoma." (PMID 26187152, 2015). "The activity of vandetanib for lung adenocarcinoma patients with RET translocation has been demonstrated in two case reports." (PMID 26018876, 2015). "Five genes were flagged as mutant in all 8 lung adenocarcinoma samples namely RET, APC, FGFR3, NPM1 and PDGFRA when the least stringent QBVD threshold was applied (QBVDi = 71)." (PMID 23922754, 2013). "Recently, RET gene rearrangements with N-terminal of KIF5B gene were identified in lung adenocarcinomas from large-scale sequencing." (PMID 23342255, 2012). "The recent study has been reporting the novel KIF5B/RET gene rearrangement found to occur in 2% (9/405) of Asian lung adenocarcinoma patients screened." (PMID 23342255, 2012). "Third, although this study represents the largest cohort evaluating TEs in advanced lung adenocarcinoma with RET fusions, the cohort size remains relatively small due to the rarity of RET fusions in NSCLC, limiting the ability to detect significant differences among driver genes." (PMID 40751559, 2025). "Notably, ROS1 and RET rearrangements occur in approximately 1% and 2% of lung adenocarcinoma cases, respectively." (PMID 39810398, 2025). "In conclusion, the optimal treatment approach for this particular setting of RET-TKIs-resistant lung adenocarcinoma remains undecided and might also depend on individual patient characteristics." (PMID 39372862, 2024). "Herein, we describe a case of critical and advanced lung adenocarcinoma harboring RET fusion." (PMID 39372862, 2024). "Therefore, directly comparing ROS1+ lung adenocarcinomas with ALK+ or RET+ tumors, while excluding cell lines, provides further insights into the tumor microenvironment." (PMID 39737401, 2024).